MIR92A2 (microRNA 92a-2)
Synonyms: hsa-mir-92-2; hsa-mir-92a-2; MIRN92-2; MIRN92A-2; MIRN92A2; mir-92a-2
Gene: MicroRNA gene on chromosome X (134,169,538 to 134,169,612, reverse strand). Ensembl gene ENSG00000284538.
Gene Ontology:
Biological process: miRNA-mediated post-transcriptional gene silencing
Cellular component: RISC complex
Homologues: Orthologues: chimpanzee ptr-mir-92-2 (100% identical), macaque mml-mir-92a-2 (100% identical), guinea pig MIR92A2 (95% identical), pig ssc-mir-92a-2 (95% identical), dog MIR92A-2 (79% identical), tropical clawed frog xtr-mir-92a-2 (59% identical). Paralogues in human: MIR92A1 (48% identical), MIR25 (43% identical).